SLC22A8 (solute carrier family 22 member 8)
Description:
Functions as an organic anion/dicarboxylate exchanger that couples organic anion uptake indirectly to the sodium gradient. Transports organic anions such as estrone 3-sulfate (E1S) and urate in exchange for dicarboxylates such as glutarate or ketoglutarate (2-oxoglutarate). Plays an important role in the excretion of endogenous and exogenous organic anions, especially from the kidney and the brain. E1S transport is pH- and chloride-dependent and may also involve E1S/cGMP exchange. Responsible for the transport of prostaglandin E2 (PGE2) and prostaglandin F2(alpha) (PGF2(alpha)) in the basolateral side of the renal tubule. Involved in the transport of neuroactive tryptophan metabolites kynurenate and xanthurenate. Functions as a biopterin transporters involved in the uptake and the secretion of coenzymes tetrahydrobiopterin (BH4), dihydrobiopterin (BH2) and sepiapterin to urine, thereby determining baseline levels of blood biopterins. May be involved in the basolateral transport of steviol, a metabolite of the popular sugar substitute stevioside. May participate in the detoxification/ renal excretion of drugs and xenobiotics, such as the histamine H(2)-receptor antagonists fexofenadine and cimetidine, the antibiotic benzylpenicillin (PCG), the anionic herbicide 2,4-dichloro-phenoxyacetate (2,4-D), the diagnostic agent p-aminohippurate (PAH), the antiviral acyclovir (ACV), and the mycotoxin ochratoxin (OTA), by transporting these exogenous organic anions across the cell membrane in exchange for dicarboxylates such as 2-oxoglutarate. Contributes to the renal uptake of potent uremic toxins (indoxyl sulfate (IS), indole acetate (IA), hippurate/N-benzoylglycine (HA) and 3-carboxy-4-methyl-5-propyl-2-furanpropionate (CMPF)), pravastatin, PCG, E1S and dehydroepiandrosterone sulfate (DHEAS), and is partly involved in the renal uptake of temocaprilat (an angiotensin-converting enzyme (ACE) inhibitor). May contribute to the release of cortisol in the adrenals. Involved in one of the detoxification systems on the choroid plexus (CP), removes substrates such as E1S or taurocholate (TC), PCG, 2,4-D and PAH, from the cerebrospinal fluid (CSF) to the blood for eventual excretion in urine and bile (By similarity). Also contributes to the uptake of several other organic compounds such as the prostanoids prostaglandin E(2) and prostaglandin F(2-alpha), L-carnitine, and the therapeutic drugs allopurinol, 6-mercaptopurine (6-MP) and 5-fluorouracil (5-FU) (By similarity). Mediates the transport of PAH, PCG, and the statins pravastatin and pitavastatin, from the cerebrum into the blood circulation across the blood-brain barrier (BBB). In summary, plays a role in the efflux of drugs and xenobiotics, helping reduce their undesired toxicological effects on the body (By similarity).
Synonyms: OAT3
Tractability: Small molecule: an approved drug acts on it; a high-quality ligand is known; it belongs to a druggable protein family. Antibody: UniProt places it where antibodies can reach, with high confidence; its Gene Ontology location is reachable by antibodies, with high confidence; UniProt predicts a signal peptide or a membrane-spanning region. PROTAC: a small molecule that binds it is known.
Target class: SLC superfamily of solute carriers; Electrochemical transporter; SLC22 family of organic cation and anion transporters; Transporter
Gene: Protein-coding gene on chromosome 11 (62,989,154 to 63,017,561, reverse strand). Ensembl gene ENSG00000149452.
Subcellular location: Basolateral cell membrane
Pathways (Reactome):
Drug ADME: Ciprofloxacin ADME
Transport of small molecules: Organic anion transport by SLC22 transporters
Gene Ontology:
Molecular function: prostaglandin transmembrane transporter activity; solute:inorganic anion antiporter activity; transmembrane transporter activity; xenobiotic transmembrane transporter activity; antiporter activity
Biological process: prostaglandin transport; transmembrane transport; transport across blood-brain barrier; xenobiotic transport
Cellular component: apical plasma membrane; basolateral plasma membrane; extracellular exosome; plasma membrane; basal plasma membrane; membrane
Genetic constraint (gnomAD): Loss-of-function variants: 32 observed, 42.84 expected, observed/expected ratio (o/e) 0.75, 90% interval 0.56 to 1. The upper end of that interval is the gene's LOEUF score, 1, which puts it in group 4 of 6, group 1 being the genes least tolerant of losing a copy. Missense variants: 587 observed, 695.29 expected, observed/expected ratio (o/e) 0.84, 90% interval 0.79 to 0.9. Synonymous variants: 258 observed, 286.07 expected, observed/expected ratio (o/e) 0.9, 90% interval 0.81 to 1.
Homologues: Orthologues: chimpanzee SLC22A8 (99% identical), macaque SLC22A8 (96% identical), rat Slc22a8 (79% identical), pig SLC22A8 (79% identical), dog SLC22A8 (78% identical), mouse Slc22a8 (77% identical), guinea pig SLC22A8 (75% identical), tropical clawed frog slc22a8 (50% identical), zebrafish slc22a6l (49% identical), Caenorhabditis elegans oct-1 (30% identical), Drosophila melanogaster Orct (28% identical), Drosophila melanogaster Orct2 (28% identical), and 37 more. Paralogues in human: SLC22A6 (51% identical), SLC22A11 (42% identical), SLC22A12 (42% identical), SLC22A24 (39% identical), SLC22A10 (38% identical), SLC22A9 (37% identical), SLC22A25 (36% identical), SLC22A7 (35% identical), SLC22A13 (32% identical), SLC22A5 (32% identical), SLC22A2 (31% identical), SLC22A1 (31% identical), and 10 more.
Diseases named in the same sentence as SLC22A8 in open-access papers:
SLC22A8 is named in the same sentence as 63 diseases in open-access papers, as found by Europe PMC text mining. Sharing a sentence is not in itself a finding about the gene and the disease. The quoted sentences say what the papers report.
chronic kidney disease (10 papers, 2012 to 2025). Impairment of the renal function secondary to chronic kidney damage persisting for three or more months. "For example, the SLC22 genes SLC22A6/OAT1 and SLC22A8/OAT3 participate in the transport of uremic toxins during renal excretion, and accumulation of certain uremic toxins can contribute to the progression of chronic kidney disease." (PMID 36230695, 2022).
gout (8 papers, 2019 to 2024). A condition characterized by painful swelling of the joints, which is caused by deposition of urate crystals. "By PPI analysis we found evidence based on experimental determined that the identified gout causal gene SLC7A7 was strongly correlated with the targets SLC22A6 and SLC22A8 of probenecid." (PMID 39734218, 2024). "Although SLC22A6 and SLC22A8 play a key role in UA transport, the specific mechanism of these two genes in HUA and gout still needs to be further studied, so as to provide new targets for the treatment of HUA and gout." (PMID 35922835, 2022).
Obesity (5 papers, 2015 to 2025). Accumulation of substantial excess body fat. "The mEC1 population showed an obesity-induced downregulation of transporters of major ions (Slc34a1, Slc4a4, Slc22a8, Slc13a1, Slc22a18 and Slc5a12), neutral amino acids (Slc6a19) and glucose (Slc5a2)." (PMID 36400935, 2022). "Furthermore, obesity led to the up-regulation of sodium transporters (Slc13a1, Slc22a8, Slc17a1, Slc17a3) and the down-regulation of structural proteins (Col4a3, Col4a4) as well as Na/K-ATPase subunits encoded by Atp1a1, Atp1b1, suggesting impaired sodium metabolism and underlying renal injury." (PMID 41133844, 2025). "We also identified six DMRs which mapped to obesity and related metabolic traits in the GWAS catalogue (PROX1, PHACTR1, SLC22A8, SMAD3, LCAT, DNM2)." (PMID 25651499, 2015).
kidney cancer (2 papers, 2022). Primary or metastatic malignant neoplasm involving the kidney. "The Human Protein Atlas further confirmed that SLC22A8 protein levels were lower in kidney cancer tissues than in normal tissues." (PMID 36123895, 2022). "A number of the identified transporters (e.g., SLC22A12/URAT1, SLC22A6/OAT1, SLC22A8/OAT3, ABCG2) are well-established uric acid transporters; this may be clinically important since a number of studies indicate that altered uric acid levels and kidney cancer are associated." (PMID 36230695, 2022).
lymphoma (2 papers, 2021). A malignant (clonal) proliferation of B- lymphocytes or T- lymphocytes which involves the lymph nodes, bone marrow and/or extranodal sites. "SLC22A8 overexpression in lymphoma and the high affinity of SLC22A8 for bendamustine are associated with cytostatic efficiency of bendamustine in lymphoma cells." (PMID 33741523, 2021).
breast carcinoma (1 paper, 2014). "SLC22A6 and SLC22A8 mRNAs were not detectable in all analyzed breast cancer cell lines." (PMID 25496233, 2014).
epilepsy (1 paper, 2022). A brain disorder characterized by episodes of abnormally increased neuronal discharge resulting in transient episodes of sensory or motor neurological dysfunction, or psychic dysfunction. "Among them, IPA revealed that 5 genes (Gfap, Gmppa, Tubb2b, SLC22a8 and Plxnb3) were related to epilepsy or neurodevelopmental disorders." (PMID 35474103, 2022). "Interestingly, 5 genes (Gfap, Gmppa, Tubb2b, SLC22a8 and Plxnb3) among the DEGs are known to be related to epilepsy or neurodevelopmental disorders." (PMID 35474103, 2022).
Hodgkin’s disease (1 paper, 2022). "The drug interaction involving hOAT1 (SLC22A6) and hOAT3 (SLC22A8), responsible for renal tubular methotrexate secretion, has also been described in a Japanese patient with Hodgkin’s disease." (PMID 36015138, 2022).
lung carcinoma (1 paper, 2019). "Expression of SLC22A8 was considered as a valuable biomarker for the lung cancer treatment." (PMID 31207989, 2019).
neuropathies (1 paper, 2024). "In one study, expression levels of 2 genes(MKI67 and SLC22A8) were associated with neuropathies in rats receiving linezolid." (PMID 38939039, 2024).
renal clear cell carcinoma (1 paper, 2022). "Next, we investigated the expression levels of methylation of SLC22A8 in renal clear cell carcinomas with different clinical features using the UALCAN database." (PMID 36123895, 2022). "The CPTAC database results showed that total SLC22A8 protein was expressed at significantly lower levels in renal clear cell carcinoma tissues than in normal tissues (P = 2.9e–40)." (PMID 36123895, 2022). "For this reason, insight into the mechanisms of differential SLC22A8 expression in renal clear cell carcinoma could provide a theoretical basis for the development of new cancer treatment strategies." (PMID 36123895, 2022). "However, little is known about the expression and regulation of SLC22A8 in renal clear cell carcinoma." (PMID 36123895, 2022).
schizophrenia (1 paper, 2025). A major psychotic disorder characterized by abnormalities in the perception or expression of reality. "However, HAL action dysregulated other genes also associated with schizophrenia in humans, such as Col6a3, Slc22a8, and Bmal1." (PMID 39825014, 2025). "HAL and KARI201 antipsychotic effects were associated with targeting expression of other schizophrenia associated genes like Col6a3, Slc22a8, and Bmal1, or Nr2f6a, respectively, but none affecting expression of sphingolipid regulating genes." (PMID 39825014, 2025).
cancer (10 papers, 2020 to 2025). A tumor composed of atypical neoplastic, often pleomorphic cells that invade other tissues. "Given its role in cancer drug resistance, dysregulated SLC22A8 expression may be a key risk factor for drug resistance of HCC." (PMID 33741523, 2021). "Because these are transporters of endogenous metabolites and drugs—and, in the case of SLC22A6, SLC22A8, SLC22A12, established drug targets—these observations are of interest from both the viewpoint of cancer biology and therapeutics." (PMID 36230695, 2022). "Six of these genes were not expressed or were very weakly expressed (ABCC11, SLC22A6, SLC22A7, SLC22A8, SLC22A9, SLCO1B1), and among the other eight genes, only gene ABCG2 showed significant difference in expression in cancer versus adjacent control tissue." (PMID 33917029, 2021). "Similarly, mining the TCGA and GTEx datasets revealed no or very low expression of genes coding hOAT1 (SLC22A6) and hOAT3 (SLC22A8) in most cancer types except for brain and renal tumours (data not shown)." (PMID 31659416, 2020).
tumor (7 papers, 2020 to 2022). "SLC22A8 expression is associated with age, grade, stage, and tumor status." (PMID 36123895, 2022). "SLC22A8 was associated with immune infiltration and could influence tumor progression through abnormal tumor microenvironment and immune response." (PMID 36123895, 2022). "It is well documented that ccRCC is one of the most immune-infiltrated tumors, however, little is known about the function and role of the SLC22A8 molecule in tumor immune relevance." (PMID 36123895, 2022). "A total of 281 variants were associated with tumor necrosis and five of these variants, in SLC22A1, SLC22A8, CHST12 and UGT2B15, were also associated with OS, prioritizing these for future research." (PMID 36536332, 2022). "Comprehensive analysis of tumor immune infiltration and the tumor microenvironment indicated a higher level of overall immunity in the SLC22A8 low expression group." (PMID 36123895, 2022). "To further clarify the correlation between diverse tumor-infiltrating immune cells and survival predictions, we performed a Kaplan–Meier survival analysis of SLC22A8 gene expression in ccRCC." (PMID 36123895, 2022). "Immunological characterization of SLC22A8 regarding the ccRCC tumor microenvironment was carried out by the single sample Gene Set Enrichment Analysis algorithm and the CIBERSORT algorithm." (PMID 36123895, 2022). "In the future, prospective studies on the role of SLC22A8 in tumor immune infiltration are needed as well as the development of novel antitumor immunotherapeutic agents targeting SLC22A8." (PMID 36123895, 2022). "We further analyzed the correlation between SLC22A8 expression and immune cell markers using the TIMER and GEPIA databases, including B cells, CD8+ T cells, M1/M2 macrophages, tumor-associated macrophages (TAMs), neutrophils, natural killer cells, and dendritic cells in KIRC." (PMID 36123895, 2022). "We further utilize bulk RNA-seq data and found a significant upregulation of SOX9, IL32, and SLC22A6 (PT2), and downregulation of SLC22A6/ SLC22A8 (PT1) in tumor compared to adjacent normal tissue, confirming our cell origin hypothesis on PT2 cells." (PMID 36180422, 2022). "Five of those are found in comparisons of both tumor types: SLC22A6/OAT1, SLC22A7/OAT2, SLC22A8/OAT3, SLC22A12/URAT1, SLC22A13/ORCTL3." (PMID 36230695, 2022). "The results showed that the SLC22A8 low expression group had a higher immune score, stromal score, ESTIMATE score, and lower tumor purity compared to the SLC22A8 high expression group." (PMID 36123895, 2022). "It is not difficult to conclude that the immune response of tumor cells was generally activated in the SLC22A8 low expression group." (PMID 36123895, 2022). "Interestingly, of the DE genes between tumor and normal kidney tissue (in bold), SLC22A6, SLC22A7, and SLC22A8 are OAT1, OAT2, and OAT3." (PMID 36230695, 2022).
nervous system diseases (2 papers, 2023 to 2024). "The important functional genes found in this study, such as SLC22A8, ADCYAP1R, and KCNIP4, will be important candidates for further research on the molecular signaling pathways of mental and nervous system diseases." (PMID 37491364, 2023).
infection (1 paper, 2019). The state of being infected such as from the introduction of a foreign agent such as serum, vaccine, antigenic substance or organism. "In addition, we validated several additional genes (SLC22A8, RASSF9, and NEAT1) which were highly upregulated in Huh7.5.1 cells, yet not within this infection responsive cluster, as controls." (PMID 30700707, 2019).
SLC22A8 also shares sentences with these, for which no sentence is quoted: hyperuricemia (26 papers); diabetes (4); acute kidney injury (3); Hyperglycemia (3); influenza (3); kidney disease (3); acute lymphoblastic leukemia (2); cholestasis (2); chronic kidney failure (2); Hypertension (2); Hypoglycemia (2); Insulin resistance (2); kidney failure (2); liver disease (2); renal failure (2); type 2 diabetes (2); alcoholism (1); anemia (1); Ascites (1); brain tumours (1); carnitine deficiency (1); chronic heart failure (1); cystic fibrosis (1); diabetic nephropathy (1); Flavivirus Infections (1); gastric ulcer (1); glioblastoma (1); Glomerular sclerosis (1); hepatocellular carcinoma (1); hyperlipidemia (1).
A further 17 diseases each share a sentence with SLC22A8 in 1 paper.